IL1B (interleukin 1 beta)
Diseases named in the same sentence as IL1B in open-access papers (continued):
Sharing a sentence is not in itself a finding about the gene and the disease.
viral infection (continued). "Moreover, viral infections can trigger the release of pro-inflammatory cytokines, such as interleukin-1 beta (IL-1β) and TNF, which further contribute to beta cell damage and dysfunction." (PMID 38239343, 2023). "In parallel with this we propose that IFN-stimulated factors may regulate deposition of repressive histone marks like H3K27me3 at specific genes, e.g. IL-1β during viral infections." (PMID 37435074, 2023). "Moreover, the serum IL-1β level was extremely low during the entire course of virus infection in patients with severe outcomes, whereas IL-6 appeared to maintain higher levels at baseline and gradually increase after infection." (PMID 37035158, 2023). "Thus caspase-1 and IL-1β pathways appear to be central in affecting polyamine metabolism dependent immune-dysfunction during viral infections." (PMID 36693889, 2023). "Moreover, the administration of VO extract reduced the release of inflammatory cytokines (TNF-α, IL-1β and IL-6) triggered by viral infection to a level comparable to that of the Control group." (PMID 37108306, 2023). "To explore the effect of SPJ treatment on cytokine expression, we used real‐time PCR and observed that viral infection led to increased expression of cytokines and chemokines, including IL‐6, IL‐1β, TNF‐α, IL‐10, IFN‐α, IFN‐β, and IFN‐γ, as well as CXCL‐2, CXCL‐10, CCL‐2, CCL‐3, and CCL‐5." (PMID 37544014, 2023). "Therefore, to further explore the role of gasdermins in the context of viral infection, the virus-induced lytic cell death and IL-1β release were assessed in cells silenced for GSDMD and GSDME expression using siRNA." (PMID 37680489, 2023). "It was possible that TNF-α, one of the first cytokines produced in response to viral infection, could trigger pro-inflammatory cascades, including IL-1β." (PMID 37048441, 2023). "Collectively, these data support the neutralization of IFN-γ and TNF, or IL-1β in the post-acute stage of viral infection as viable therapeutic options to augment alveolar regeneration and dampen fibrotic sequelae observed following respiratory viral infections." (PMID 38077031, 2023). "Viral infection can trigger the production of IL-1β in host cells." (PMID 36503883, 2022). "Similarly, the naïve macrophages became activated in response to the viral infection and expressed essential inflammatory molecules like IL-1β, CCL3, and CCL4." (PMID 35440562, 2022). "Activation of NLRP3 or other NLR inflammasomes leading to IL-1β/IL-18 secretion and pyroptosis may also have different impact on viral infection and host cell status in different tissues and organs." (PMID 35173184, 2022). "Both IL1-β and IL-17 stimulation from the Th1/Th17 response increases the vascular permeability which results in the recruitment and infiltration of neutrophils in the affected sites and forms NETs and NETosis to clear the virus infections." (PMID 36094915, 2022). "Our findings demonstrated that DSV blocks the interaction of viral S protein with ACE 2, thereby downregulating the virus infection-induced pro-inflammatory cytokines (IL-6), (IL-1β), and (TNF-α) which are highly elevated instigating the innate anti-viral response." (PMID 36386162, 2022). "Therefore, we investigated the effects of pH240R on IL-1β production in PAMs during viral infection." (PMID 36326277, 2022). "For example, a bacterial infection could promote platelet to activate leukocytes via Toll-like receptors, and virus infection might lead to platelet releasing IL-1β, which is a core cytokine of the cascade of inflammation." (PMID 35287583, 2022). "Moreover, emerging evidence suggests that viral infection can activate inflammasomes in macrophages to produce IL-1β and IL-188,9." (PMID 36503883, 2022). "IL-1β and IL-6, pro-inflammatory cytokines having critical roles in infection and inflammation, have been found to be associated with severe lung injury during influenza A (H1N1) virus infection." (PMID 36106521, 2022).
viral infection (continued). "ICAM-1 expression is constitutively low at the surface of ECs and may be upregulated in response to stimuli, such as viral infection, oxidative stress, and pro-inflammatory cytokines, including interleukin-1β (IL1β), TNF-α, and interferon-γ (IFN-γ)." (PMID 35062347, 2022). "It is also known that bacterial superinfections are common after viral infections that may be partly due to the inhibitory effect of the virus-triggered IFN pathway on the bacteria-induced IL-1β pathway." (PMID 36293012, 2022). "IL-1β is a vital proinflammatory cytokine that mediates immune functions and participates in the resistance to viral infections during the early stages of infection, but an excessive increase in IL-1β may lead to increased lung injury." (PMID 33540650, 2021). "During viral infection, the formation of IL-1β has two steps, priming and maturation." (PMID 33708197, 2021). "It is hypothesised that a viral infection may represent the initial stimulus capable of inducing the upregulation of IL-1β." (PMID 34445745, 2021). "However, viral infection can induce IL-1β–mediated inflammation through NLRP3-independent mechanisms." (PMID 34638790, 2021). "It has been shown that these viral infections could lead to systemic inflammation with a high level of IL-6, IL-1β, and TNFα." (PMID 33607952, 2021). "The inflammasome complexes induce the maturation of IL-1β and IL-18, which are important in the defense against viral infections because of their ability to regulate leucocyte migration to the infected area as well as to stimulate the activation and polarization of T cells." (PMID 34946051, 2021). "Virus infection of antigen presenting cells, such as dendritic cells, macrophages, and other cell types including endothelial cells, result in activation of biochemical signals, which lead to secretion of a battery of cytokines that include IL1β and IL-6." (PMID 34367726, 2021). "Indeed, BCG vaccination increases circulating IL-1β, which inversely correlates with viremia after a secondary yellow fever vaccination." (PMID 33391283, 2020). "The ratio was significantly highest just prior to peak IL1β relative transcription levels and follows the timing of increases in white blood cell counts in other reptiles viral infections, specifically in snakes with ferlaviruses between days 4 and 16 post-infection." (PMID 33119713, 2020). "IL-1β is another cytokine shown to improve the outcome of H1N1 infection by stimulating the CD8T cells and their activity while IL-6 was found to be essential for preventing death of neutrophil cells caused by the viral infection." (PMID 30288556, 2019). "ELISA analysis showed that IL-1β and IL-18 secretion was markedly augmented in Park2−/− cells relative to WT counterparts after viral infection, whereas the production of tumor necrosis factor (TNF)-α, an inflammasome-independent cytokine, was not affected by Park2 deletion." (PMID 31229895, 2019). "IL-1β is a proinflammatory cytokine, which is released following activation of inflammosomes in response to viral infection, suggesting that UCB γδ T cells might have superior properties for mounting antiviral responses." (PMID 29707004, 2018). "The response in 17D virus-infected cells was not apparent except for elevated levels of IL-1β at 1 hpi suggesting an attachment-mediated release of IL-1β that promptly decreased in 17D virus-infected cells, but that persisted with decreasing levels in Asibi virus infection." (PMID 27191161, 2016). "Despite the inability of virus infection alone to induce substantial expression of CXCL2 or IL-1β, or Ly6GhiCD11bhiCD45+ neutrophil influx, infection combined with bites induced significantly higher expression and an enhanced neutrophil influx compared to bite alone." (PMID 27332734, 2016). "Thus, intestinal Paneth cells are the earliest responders to viral infection and induce gut inflammation through IL-1β signaling." (PMID 25166758, 2014).
viral infection (continued). "NF-κB signaling, which regulates a number of inflammatory genes, including iNOS, COX-2, TNF-α, IL-1β, and IL-6, can be stimulated by pathological stimuli, such as viral infection, UV radiation, and free radicals, and its dysregulation is involved in the pathogenesis of many inflammatory disorders." (PMID 24475143, 2014). "In response to virus infection, dendritic cells produce large amounts of type I IFNs, which could act in a paracrine manner to efficiently amplify the production of IL-1β by the airway epithelium." (PMID 23592984, 2013). "Normally, virus infection may enhance IL-1α, IL-1β and TNF-α expression that consequently inhibits virus replication." (PMID 23527143, 2013). "Virus infection has been shown to induce IL-1β production through inflammasome signaling." (PMID 23633957, 2013). "Therefore, the immunopathology seen in our acute viral infection model is likely to be related to activation of inflammasome pathway and excessive IL-1β production." (PMID 22558229, 2012). "Therefore, a fine balance of IL-1β-mediated signaling appears to be important for protection from viral infections." (PMID 22985464, 2012). "Similarly, RS viral infection induces the release of IL-1β, IL-6, and IL-8 from human airway and alveolar epithelial cells." (PMID 22966430, 2012). "In particular, TNFα concentration per se enables the recognition of COPD exacerbations due to Pseudomonas Aeruginosa infection, while IL8 + IL1β levels prove helpful in discriminating common bacterial infection from viral infections and noninfectious causes." (PMID 17034639, 2006). "Thus, chronic viral infections involving increases in IL-1β may trigger perturbations in polyamine synthesis and Th fate decisions, which may further fuel pathogenic inflammation in the mucosa." (PMID 36693889, 2023). "Studies on pharmacological inhibition of various viral diseases have shown that inhibition of Caspase-1 could block the GSDMD-mediated cell pyroptosis process and reduce the expression levels of IL-1β and IL-18, leading to corresponding therapeutic effects on viral diseases." (PMID 38132483, 2023). "Furthermore, IL-1β and C3 expression is increased in different viral infections of the CNS." (PMID 37191498, 2023). "Therefore, IL-1β is a potential target in viral infection therapy." (PMID 36503883, 2022). "Upon infection, various cardiac-resident cells, such as cardiomyocytes, endothelial cells, mast cells, phagocytes, and fibroblasts, secrete cytokines IL-1β, and IL-18, contributing to acute inflammation, and treatment with IL-1β could break the resistance of C57Bl/6 (H‐2b) mice to viral infection." (PMID 35997820, 2022). "In addition, excessive and uncontrolled production of TNF-α, IL-1β, IL-6, and other inflammatory cytokines by macrophages may result in serious systemic complications during viral infections such as tissue damage and septic shock." (PMID 34946051, 2021). "To exclude the possibility that the enhanced inductions of IL-1β and IFN-β by ASFV-Δ7R was due to more virus particles or increased host cell viability instead of loss of functions of pMGF505-7R, we detected the viral genomic copy numbers and cellular viabilities following viral infections." (PMID 34310655, 2021). "During the process of viral infection, PRRs in the host cells recognize conserved microbial components called PAMPs and trigger a series of signals that induce production of inflammatory cytokine IL-1β, type I IFNs and other downstream effectors to antagonize viral infection." (PMID 34310655, 2021). "In addition, the damage to endothelial cells after viral infection and/or activation of endothelium by pro-inflammatory cytokines, such as IL-1β, IL-6, IFN-γ, IL-8, and TNF-α induces platelets and monocyte aggregation in the vascular wall and expression of tissue factor (TF)." (PMID 33357215, 2020). "In addition, IL-1β mRNA levels were increased 12 h after virus infection." (PMID 28878777, 2017).
viral infection (continued). "In rodent models, in utero viral infection mimicked by the administration of polyriboinosinic:polyribocytidylic acid (poly(I:C) resulted in the post-pubertal emergence of brain immune changes (specifically, IL-1β and TNF-α) and anxiety-related behaviors in the offspring." (PMID 27244231, 2016). "Moreover, both IL-1β and dsRNA become available during viral infection." (PMID 22590509, 2012). "Induced by a series of other cytokines as IL1A (IL1A fold regulation = 2.99), IL1B (IL1B fold regulation = 10.76), IL7, TNF (TNF fold regulation = 2.39), LPS or viral infections, CCL5 behaves like a proinflammatory cytokine." (PMID 40149697, 2025). "During viral infection, a complex cascade involving NLRP3, ASC and Pro-caspase-1 forms to process the precursors of IL-1β and IL-18 into active forms." (PMID 39038050, 2024). "This systematic review identified that in vitro evaluation of proinflammatory cytokines released by microglia against viral infections, mainly the cytokines IL-6, TNF-α and IL-1β, was frequently compared to the evaluation of anti-inflammatory cytokines." (PMID 38349562, 2024). "TNF-α, IL-6, and IL-1β play a critical role in various inflammatory diseases, while MCP-1 expression is correlated with the pathogenesis of certain diseases or viral infections." (PMID 38275672, 2024). "The early induction of Th1 cytokines such as IL-1β and IL-18 is protective to infected hosts by promoting CD8+ T-cell activity and antibody responses, and IL-27 is effective against viral infections by decreasing immunopathology and increasing survival." (PMID 39066362, 2024). "GAS6 mRNA was decreased in the MSCs stimulated with recombinant IL-1β, TNF-α, TGFβ1 (produced by MSC), and PDGBB (produced by endothelial cells) at 6 h, while poly I:C, known to mimic viral infections, increased GAS6 expression." (PMID 37958918, 2023). "Higher levels of inflammatory mediators like IL-25, IL-1β, IL-10, IL-5 and tumor necrosis factor (TNF) -α after viral infection were found in human nasal epithelial cell (HNEC) culture compared to controls." (PMID 38116043, 2023). "IL-1β leads to IFN production and activation of IFN signaling and induces a potent innate immune response against viral infections." (PMID 36673407, 2023). "The mRNA levels of IL-1β, IL-6, and IL-8 showed a trend of decreases and then increases, while the mRNA levels of TNF-α and IL-10 significantly increased after viral infection." (PMID 36995259, 2023). "In this study, we identified the ASFV pI10L as an inhibitor of virus-induced inflammatory responses following viral infection and treatment with TNF-α or IL-1β." (PMID 37607059, 2023). "We found that virus-induced mRNA levels of key proinflammatory cytokines, IL6, IL1B, CCL2, and CXCL10, were decreased in monocytic cell lines, namely THP1 and U937, and in PBMCs treated with Senexin B prior to viral infection." (PMID 37376593, 2023). "Acute viral infections of the upper aerodigestive tract induce various proinflammatory cytokines, including IFN-γ, IL-1β, and IL-6." (PMID 35915851, 2022). "We validated this finding through RT-qPCR, confirming that the expression of the proinflammatory factors IL-1β, CCL4, TNF and CXCL8 decreased progressively with viral infection." (PMID 36544767, 2022). "NF-κB and P38 MAPK are critical regulators involved in the regulation of proinflammatory cytokines, which can be activated by viral infection or several cytokines (e.g., TNF-α and IL-1β)." (PMID 36180831, 2022). "In contrast, significant induction of IL-1β and IL-18, was only observed in THP1/PMA CD169+ macrophages and primary MDMs, suggesting that CD169-mediated viral infection uncouples induction of inflammatory responses from robust viral replication." (PMID 36279285, 2022). "While the axes IL-1β/IL-6 link to CRP production in bacterial infections, IL-18 production links to transferrin in viral infection." (PMID 35663992, 2022).
viral infection (continued). "In particular, type I IFNs inhibit NLRP3 inflammasome-dependent IL-1β production through different mechanisms, which might explain why the body’s antibacterial defense mechanism is weakened and more prone to bacterial superinfections following severe viral infections." (PMID 36293012, 2022). "qRT-PCR analyzed the immune genes, including IL-1β, TRAF3, TNF-α, and TLR2 expression levels in JFSP cells after virus infection." (PMID 36552207, 2022). "Pro-inflammatory cytokines, such as IL-6, IL-1β, and TNF-α, are significantly increased during viral infections and exacerbate lung tissue damage." (PMID 36147321, 2022). "Only IL-1β and IFN-α2 were detected in higher levels in response to the single viral infection as compared to uninfected controls (online suppl." (PMID 35249041, 2022). "The increase in IL-1β, IL-6, IL-4, and TNF-α expression in the spleen indicates the activation of the immune system, resulting in resistance to virus and prevention of virus infection." (PMID 36177044, 2022). "NF-κB activation in patients with COPD occurs in response to inflammatory mediators such as IL-1β and TNF-α or due to activation of Toll-like receptors (TLRs) following bacterial or viral infections." (PMID 35517806, 2022). "The authors showed that host IL-1β increases in infected animals with both IL-1β and NLRP3 acting as restriction factors to control viral infection in the CNS." (PMID 36298668, 2022). "Notably, HIF-1α, IL-1β, IL-6, and IFN-β mRNAs and HIF-1α protein were induced in infected cells, suggesting that HIF-1α and immune and inflammatory cytokines are induced upon the virus infection, and HIF-1α expression is linked to immune-inflammatory cytokine expression in infected cultured cells." (PMID 34408131, 2021). "Bacterial or viral infection activates NF-κB through toll-like receptors, resulting in the production of proinflammatory cytokines including TNF-α, IL-1β, and IL-6." (PMID 34393799, 2021). "Compound 4a antagonist binds to TLR3/dsRNA to suppress TLR3 activity in gastrointestinal viral infections as well as the expression of downstream TLR3/dsRNA signaling pathways, including TNF-α and IL-1β." (PMID 34659656, 2021). "As key components of intercellular signal transmission and regulation, the expression of cytokines including inflammatory factors (IL-1β and IL-8) and toll-like receptors (TLR2, TLR3, and TLR7) increased significantly after viral infection." (PMID 33897703, 2021). "All these virus infection induced gene transcriptions of IFNβ, ISG56, TNFα, IL1β and IL8 were reduced in in LGP2-/-, RIG-/- and MDA5-/- PAMs compared with control PAMs." (PMID 34093517, 2021). "It would be interesting to determine how IL-1β, IL-23, IL-15, and other cytokines are dynamically regulated to control MAIT cell-mediated immune protection, as well as pathogenesis during viral infections and other inflammatory conditions in the future." (PMID 33795689, 2021). "Consistently, it was reported that not only interferon treatment or viral infection increased ACE2 levels, several inflammatory cytokines stimulation, such as TNFα, IL6 and IL1β, also increased the level of ACE2." (PMID 34867400, 2021). "ALI and ARDS are characterized by overproduction of pro-inflammatory cytokines such as IL-1β, TNF-α, and IL-6 as a result of bacterial or viral infection, trauma, excess exposure to oxygen and noxious gases." (PMID 33806560, 2021). "At the same time, IL-1β, IL-4, IL-6, IFN-γ, GM-CSF, and TNF-α activate inflammatory effector mechanisms typical of a viral infection." (PMID 34831403, 2021). "IL-6 is a highly inducible pro-inflammatory cytokine secreted by several cell types including monocytes, lymphocytes, fibroblasts and endothelial cells; interleukin-1β (IL-1β) and TNF-α, viral infection and Angiotensin II are able to induce IL-6." (PMID 34001199, 2021).